PARP1 (poly(ADP-ribose) polymerase 1)
Diseases named in the same sentence as PARP1 in open-access papers (continued):
Sharing a sentence is not in itself a finding about the gene and the disease.
cancer (continued). "Considering PARP1’s role in the DDR and having in mind that genome instability is one of the hallmarks of cancer, the idea of developing PARPi arose in oncology studies." (PMID 36533080, 2022). "PARP1 is therefore proposed to promote KLF4 binding to its promoter to maintain TERT expression in stem and cancer cells, thereby contributing to pluripotency and cell proliferation." (PMID 35348914, 2022). "PARP1 inhibitors, such as Olaparib, Rucaparib, Niraparib, and Talazoparib, have been approved by the FDA to treat cancers." (PMID 35998296, 2022). "After examining the pulled‐down proteins by lncRNA ARHGAP5‐AS1 using mass spectrometry proteomics, we identified multiple cancer‐related proteins including CSDE1, ZC3HAV1, CCT8, CKAP4, PARP1, PEG10 and APEX1 in HepG2." (PMID 36354136, 2022). "Such clinical PARPi exclusively target PARP-1 and PARP-2 to execute their anti-cancer effects through a synthetically lethal interaction with HR defects." (PMID 36428712, 2022). "Poly (ADP-ribose) polymerase 1 (PARP-1) is a critical enzyme involved in DNA damage repair and recombination, and shows great potential for drug development in the treatment of cancers with defective DNA repair." (PMID 36353483, 2022). "In 2011, it was proposed that gelomulide K, a diterpene, can induce PARP1 (poly(ADP-ribose) polymerase 1) hyperactivation, AIFM/AIF nuclear translocation and cytoprotective autophagy in cancer cells." (PMID 36497321, 2022). "With the knowledge that SSBs that were unresolved by PARP1 became DSBs with replicative stress that requires BRCA1/2 for repair, the idea of cancer DNA damage response (DDR) synthetic lethality was tested." (PMID 35800362, 2022). "When PARP-1 is inhibited by PARP inhibitor, cancer cells with HRD are unable to repair DNA damage by HR and BER, leading to cell death (synthetic lethality)." (PMID 36233090, 2022). "The phosphorylation of PARP1 by c-Met (pY907) enhances PARP1 enzymatic activity and decreases binding to PARPI, resulting in resistance of cancer cells to PARPIs." (PMID 35785170, 2022). "In order to promote the apoptosis of cancer cells, Yu Rao’s research group created an MDM2-based PROTAC that targets PARP1 to obtain a new therapeutic weapon in BC." (PMID 36232374, 2022). "In mesenchymal cancer stem cells, NNMT overexpression depleted intracellular NAM and therefore enhanced the activity of PARP1, increasing the chemoradiotherapy resistance of cancer cells." (PMID 35338115, 2022). "Human cancer cells use both proteasome‐dependent and proteasome‐independent endonucleolytic pathways (TDP1, PARP1, XPF‐ERCC1, MRE11, CTIP, and MUS81‐EM1) to remove TOP1cc." (PMID 35582959, 2022). "PARP1, poly ADP-ribose polymerase I, was investigated to be highly expressed in HCC and became a promising target for cancer therapy 20-22." (PMID 35517402, 2022). "There are currently a number of clinical PARPi, including olaparib, niraparib, rucaparib and talazoparib, that have potent and selective catalytic inhibitory activity against PARP1 and PARP2, and are used in cancer treatment." (PMID 36568963, 2022). "The remaining shared hits in the 5 cancer cell lines included X-Ray Repair Cross Complementing 1 (XRCC1), PARP1, Replication Protein A1 (RPA1) and DNA ligase 3 (LIG3)." (PMID 36386669, 2022). "Olaparib is an FDA-approved dual PARP-1 (IC50 = 0.005 μM) and PARP-2 (IC50 = 0.001 μM) inhibitor for the treatment of cancer." (PMID 36304149, 2022). "The drugs cause the blocking repair of DNA single-strand breaks (SSBs), which allow progressing DNA damage to double-stranded breaks (DSBs), as well as trap the PARP1 and PARP2 enzymes at damaged DNA that induces synthetic lethality of cancer cells." (PMID 35408658, 2022). "These compounds were evaluated for their PARP-1 enzyme inhibitory activity and cellular inhibitory against MCF7 and HCT116 human cancer cell lines." (PMID 35424391, 2021).
cancer (continued). "PARP1 and PARP2 are recognized as increasingly important targets for cancer therapy with now four clinically approved compounds (olaparib, rucaparib, niraparib, and talazoparib) in use for treatment of breast and ovarian cancer." (PMID 33531508, 2021). "PARPi blocks PARP1’s function and inevitably generates cytosolic DNA in BRCA mutant cancer cells, which triggers the cGAS-STING signaling pathway." (PMID 34367175, 2021). "In both cancer cell lines, Twist amplification coincided with an increased expression of DNA damage response (DDR) genes, including PARP1 and XRCC1." (PMID 33920140, 2021). "The C-Met-dependent PARP1 phosphorylation at Tyr907 increases PARP1 activity and results in a reduced affinity to PARP inhibitors, thereby rendering cancer cells resistant to PARP inhibitors." (PMID 34639169, 2021). "Here, we report that the coordinated actions of MYC, PARP1, and ATM assist cancer cells in acquiring cisplatin resistance by BIN1 deficits." (PMID 34948122, 2021). "Thus, compounds which cleave PARP1 may be useful in cancer chemotherapy." (PMID 34940290, 2021). "Compared with PARP1/2, other members of the PARP family have been investigated in a limited number of studies; however, their importance in cancer has attracted increased attention in recent years." (PMID 34976832, 2021). "ASA-A, ASA-B, ASA-C and POPA generated a statistically significant enhancement and increase of the PARP1 and PARP2 mRNA expression in all tested cancer cell lines." (PMID 34440232, 2021). "High levels of APEX1 (apurinic/apyrimidinic endodeoxyribonuclease 1) and PARP1 (poly(ADP-ribose) polymerase 1), involved in base exchange repair (BER), confer chemoresistance in several types of cancer." (PMID 33918653, 2021). "The overlapping roles of PARP1 and PARP2 in DNA damage response (DDR) and the fact that most PARPis target both enzymes suggest that PARP2 also contributes to PARPi-induced cancer cell death." (PMID 33922595, 2021). "PARP1 is the best-characterized member of this family and plays a pleiotropic role in DDR, thus becoming an attractive target for cancer therapy." (PMID 34439854, 2021). "Several PARP1 and PARP2 inhibitors are currently employed in the clinic or undergoing trials for treatment of various cancers." (PMID 34210965, 2021). "All the newly synthesized compounds were evaluated for their inhibitory activity towards PARP-1 and examined for their anti-proliferative activity against MCF-7 and HCT116 human cancer cell lines." (PMID 35424391, 2021). "On the other hand, increased activity of PARP1 may initiate the T-cell factor/lymphoid enhancer-binding factor, a protein family of transcription factors, which under normal conditions controls organ development, while its appearance in cancers promotes its progression (e.g., colon cancer)." (PMID 33572647, 2021). "Of particular note, pharmacological inhibitors of the BER enzyme PARP1 [poly(ADP-ribose) polymerase 1], such as niraparib, olaparib, and rucaparib, are widely used for targeted cancer therapy." (PMID 33898418, 2021). "In general, the results indicated that the PARP1/ACTB and PARP2/ACTB mRNA cellular content ratios are notably increased (t-test, p < 0.001) in most cases and for all tested cancer cell lines after treatment with the alkylators ASA-A, ASA-B, ASA-C and POPA." (PMID 34440232, 2021). "As olaparib, a PARP1 inhibitor, is widely used in cancer therapy, RIF1 can be considered a prognostic marker in olaparib-based anti-cancer treatment." (PMID 34768871, 2021). "For instance, BER-related genes such as PARP-1, DNA Polb, XRCC1, Lig I have been found to be up-regulated in a functionally meaningful way in HPV+-HNSCC cancers." (PMID 34490123, 2021).
cancer (continued). "Although cancer cells differ from primary macrophages in inter alia expression of LPS receptor CD14, they responded similarly to LPS also in terms of PARP1 contribution to the induction of endotoxin tolerance." (PMID 33671709, 2021). "The increased expression of PARP1 observed in this study indicates that pre-treatment of EC cells with MSM before DOX exposure increases DNA damage and cancer cells death." (PMID 32562081, 2021). "PARP1 and PARP2 have been extensively studied for their roles in DNA repair and as targets for cancer therapeutics." (PMID 35096828, 2021). "Combined treatment of Talazoparib plus IR tended to decrease PARP1 in ARPA, RERO and LIWE cancer cell cultures." (PMID 34073147, 2021). "PARP1 (and PARP2) are important targets for cancer therapy with now four clinically approved compounds (olaparib, rucaparib, niraparib, and talazoparib) in use for treatment of breast and ovarian cancer." (PMID 33683197, 2021). "Particularly, Poly (ADP-ribose) polymerase-1 (PARP-1) is a DNA binding protein able to modulate gene transcription and mediate several cellular pathways involving DNA duplication and repair, cancer and apoptosis." (PMID 34440548, 2021). "Since PARP-1 represent an abundant nuclear enzyme, Auger-emitting PARP-radioligands exhibit a relevant potential to deliver a cytotoxic effect to cancer cell DNA." (PMID 33809749, 2021). "Tissue expression was confirmed to be significantly different in cancer vs. control samples for DNA2, MAOA, PARP1, TYR, and HDAC1 in the IST Online database and for PTK2B, MAOA, PARP1, and TYR in the GEPIA2 database." (PMID 34199192, 2021). "One is the PARP1-MYC pathway for BIN1 reduction, which spontaneously emerges when cancer cells become cisplatin-resistant, and the other is the ATM-phosphorylated MDC1-RNF8 signaling pathway by a BIN1 loss." (PMID 34948122, 2021). "PARP1, a critical BER enzyme, resides at the nexus of autophagy and BER pathways and acts as a regulator in both cancer and cell death." (PMID 34377049, 2021). "The rapid development of PARP1/2 inhibitors for the treatment of ovarian and breast cancers has advanced research on other PARP family members for the treatment of cancer." (PMID 34976832, 2021). "One of the important functions of PARP-1 is inducing the response to DNA damage, and the upregulation of PARP-1 in cancer along with its pivotal role in DNA repair has led to the investigation of the targetability of this critical enzyme." (PMID 33805293, 2021). "USP11 is often overexpressed in cancer and induces resistance to poly(ADP-ribose) polymerase 1 (PARP1) inhibitors." (PMID 32296023, 2020). "Moreover, PARP1 has been implicated in the protection and stabilization of stalled replication forks due to replication stress—a function that gains extreme importance in BRCA1/2-deficient context and rationalizes once more the use of PARPi in treating BRCA-deficient cancer patients." (PMID 32784607, 2020). "Poly(ADP-ribose) polymerase-1 (PARP-1), a critical DNA repair enzyme in the base excision repair pathway, has been pursued as an attractive cancer therapeutic target." (PMID 32779949, 2020). "PARP1 was proposed as a new treatment for cancer, as the synthetic lethality concept suggested that its depletion in breast-cancer patients with germline mutations in the BRCA1 or BRCA2 genes, key molecules in the homologous recombination (HR) pathway, could cause cancer cell death." (PMID 32046300, 2020). "Emerging evidence supporting the immunomodulatory roles of PARP-1 and PARP-2 has raised the prospect of harnessing PARP inhibition to not only target the cancer itself, but also therapeutically modify its microenvironment." (PMID 32046278, 2020).
cancer (continued). "This study reveals a novel role for KLF4 PARylation in DNA damage response in cancer, and reports a synergy between targeting KLF4 and PARP1 in the treatment of triple negative breast cancer (TNBC)." (PMID 33231937, 2020). "This anti-cancer effect is due to activation of caspase-3 and poly [ADP-ribose] polymerase 1 (PARP-1), which are concomitant to the inhibition of the Akt pathway." (PMID 32075265, 2020). "The various factors that trigger necroptosis in cancer cells include cytokines, RIP1, RIP3, poly(ADP-ribose) polymerase-1 (PARP-1), Ca2+, and ROS." (PMID 32334473, 2020). "Recently, a potent, orally available, and highly selective PARP-1 inhibitor named NMS-P118 was discovered and in preclinical studies for cancer therapy." (PMID 32373627, 2020). "However, the applicationof SL modulators still has a long way to go, as not all cancer subtypeshave clearly defined deficiency, such as has been seen with the applicationof PARP1 and BRCA1/2 inhibitors or the 29 clinical trials currentlyinvolving ATR inhibitors." (PMID 33135887, 2020). "The roles of PARP-1 inhibitors such as ANI and 3-AB in cancer chemotherapy have been reported previously." (PMID 33158052, 2020). "PARPs have been studied as potential targets for drug development, with PARP1, and more recently PARP14, attracting the most attention in the cancer field." (PMID 33053746, 2020). "The most frequently amplified genes across the Pan-Cancer Atlas were NBN (n = 4,275, 40.8%), EXO1 (n = 3,714, 35.4%), PARP1 (n = 3,695, 35.2%), PRKDC (n = 3,650, 34.8%) and POLB (n = 2,794, 26.6%)." (PMID 32226530, 2020). "One of the views is that inhibitors of parthanatos, such as PARP1 inhibitors, could facilitate cancer cell death via inhibiting the DNA repair needed for cell survival, while other ideas are that inducers of parthanatos could directly promote cancer cell death." (PMID 33665167, 2020). "Following PARP1 and PARP2, PARP3 has also been described as a potential therapeutic target in certain cancers." (PMID 32151005, 2020). "Across all 6 cancer types, APE2 expression was significantly positively correlated with the expression of PCNA, APE1, PARP1 and XRCC1 yet expression ranges varied per cancer type and gene-gene pair." (PMID 32111912, 2020). "In view of the decreased expression of PARP1 and NFkappaB in several cancer cell types eradicated by PJ34, it has been suggested that eradication by PJ34 can be attributed to the attenuation of PARP1-dependent NF-kappaB activity that promotes proliferation." (PMID 32575437, 2020). "By immunofluorescence, we found that PARP1 partially colocalized with FGFR1 in the cell nucleus in the FGFR1-expressing, PARP1-expressing PANC-1 cancer cell line." (PMID 32276472, 2020). "Here, we report the novel finding that (ADP‐ribosyl)ation (PARylation) of KLF4 by Poly [ADP‐ribose] polymerase 1 (PARP1) regulates KLF4 chromatin recruitment following DNA damage response, which provides potential novel strategies for targeted cancer therapy." (PMID 33231937, 2020). "The selective inhibition of PARP1 by olaparib synergized with exposure to PD173074 to elicit significant suppression of PDAC stem cell viability and related cancer stem cell-like phenotypes." (PMID 32276472, 2020). "There are several studies showing the potential of combination therapy based on irradiation and various DDR inhibitors (DNA-dependent protein kinase (DNA-PK), ATM/ATR, LIG4, PARP1, CHK1) but mainly in other types of cancer." (PMID 32605254, 2020).
cancer (continued). "We have shown that APE2 expression is positively correlated with the expression of PCNA, APE1, PARP1, XRCC1, Chk1, and Chk2 across all six cancer types analyzed in this work." (PMID 32111912, 2020). "Interestingly, PARP1 and NFκB mediated mechanisms have been shown to regulate secretory phenotype in senescent cells, which might be necessary for cancer cells to recruit macrophages after chemotherapy treatment and thus may negatively affect the outcome of the procedure." (PMID 32455851, 2020). "Finally, our results suggest that PARP-1 inhibition does not cause indiscriminate immunosuppression, which represents a trait that is very important not only for inflammatory diseases but also in cancer settings." (PMID 31178661, 2019). "The results showed that compound 5l exhibited the most potent inhibitory effects on PARP-1 enzyme (16.10 ± 1.25 nM) and MDA-MB-436 cancer cell (11.62 ± 2.15 μM), which was close to that of Olaparib." (PMID 30427217, 2019). "The protein Deleted in Breast Cancer-1 is a regulator of several transcription factors and epigenetic regulators, including HDAC3, Rev-erb-alpha, PARP1 and SIRT1." (PMID 31591441, 2019). "It has recently been shown that Ets-1 interacts with two DNA repair enzymes, PARP-1 (poly(ADP-ribose) polymerase 1) and DNA-PK (DNA-dependent protein kinase), through two different domains and that these interactions play a role in cancer." (PMID 30857266, 2019). "Among these synthesized compounds, 5l exhibited the most potent inhibitory effects on PARP-1 (16.10 ± 1.25 nM) enzyme and MDA-MB-436 (11.62 ± 2.15 μM) cancer cell, which were just a little weaker than Olaparib." (PMID 30427217, 2019). "The prognostic impact of the expression of PARP1 and PARP1-related molecules suggests the possibility that the expression of these DNA damage response (DDR) molecules may provide resistance to anti-cancer chemotherapy by preventing therapy-related cancer cell death." (PMID 29784019, 2018). "We focussed on the tumoral up-regulated lncRNAs nearby cancer-related protein coding genes and found an overexpressed lncRNA (GeneSymbol: BC032899) named lncPARP1, which was located downstream of PARP1 gene." (PMID 29776974, 2018). "A disease role for PARP-1 has been largely the domain of oncology studies, with several PARP-1 inhibitors pursued through clinical trials for various cancers." (PMID 29392078, 2018). "Here, we genetically ablated PARP1 in a BRCA1- and BRCA2-positive cancer cell line, HCT116, to better understand the role of PARP1 in an otherwise normal, albeit oncogenic, generic background." (PMID 30410680, 2018). "The type of death rescued by PARP-1 inhibition with 3-ABA was mainly achieved by a decrease in apoptosis, and also by a decrease in necrosis in cancer patients." (PMID 29472838, 2018). "Several other upstream regulators appeared to play a role in cell growth, DNA replication, and cancer (CDKN2A, TCF3, PARP1, let-7a-5p)." (PMID 30327482, 2018). "Therefore, regarding the application of PARP inhibition, our results suggest that more cases of cancers might benefit from PARP inhibition therapy because a substantial number of cases are included in the poor-prognostic group by expressing PARP1/γH2AX/BRCA1/2." (PMID 29784019, 2018).